SYP (synaptophysin)
Diseases named in the same sentence as SYP in open-access papers (continued):
Sharing a sentence is not in itself a finding about the gene and the disease.
tumor (continued). "Despite this, their immunophenotypes more closely resembled low grade lesions, with an absence of synaptophysin expression, in contrast to the occasional positive cells seen in the high grade lines, and higher grade tumours in humans." (PMID 19365568, 2009). "Immunohistochemistry reveals that the tumor is typically keratin-, vimentin-, pancreatic polypeptide-, and chromogranin-positive, with a lesser number of tumors proving to be neuron-specific-enolase (NSE), synaptophysin-, serotonin- and S-100 protein-positive." (PMID 20111612, 2009). "Immunohistyochemically, tumor cells were positive for cytokeratin, synaptophysin, neuron-specific enolase, and CD56; they were negative for chromogranin, gastrin, glucagon, somatostatin, pancreatic polypeptide, and vasoactive intestinal polypeptide." (PMID 27990210, 2009). "The tumour usually spares the mucosa, infiltrates muscularis propria and peri-appendiceal fat and can stain positively for mucin, CEA, cytokeratin, lysozyme, chromogranin A, serotonin and synaptophysin." (PMID 19171048, 2009). "Tumor cells showed diffuse immunopositivity for calcitonin, HMB-45, carcinoembryonic antigen, synaptophysin, chromogranin, vimentin and epithelial membrane antigen but focal paranuclear dot-like positivity for cytokeratin, and were negative for thyroglobulin, S-100, melan-A and TTF." (PMID 18190715, 2008). "The neuroendocrine markers CD56, chromogranin and synaptophysin were negative ruling out a neuroendocrine subpopulation of the tumor." (PMID 18279511, 2008). "Histologically, the tumor cells are polygonal with abundant eosinophilic cytoplasm and eccentric nuclei and on immunostaining, these cells are variably positive for desmin, vimentin, GFAP, CK, EMA, SMA and synaptophysin." (PMID 18439235, 2008). "The tumor cells in this case were non-immunoreactive for cytokeratins and neuroendocrine markers such as chromogranin and synaptophysin, further ruling out the possibility of poorly differentiated carcinoma of lung, both small cell and non-small cell type." (PMID 15967023, 2005). "The tumor cells demonstrated lack of immunoreactivity for cytokeratin, thyroid transcription factor-1, and usual neuroendocrine markers, synaptophysin and chromogranin in formalin-fixed cellblock sections." (PMID 15967023, 2005). "Immunohistochemical analysis disclosed positive staining to AE1/AE3, CK20, CK5/6, P40, c-kit and NCAM, and negative staining to CK-7, CK-8, AFP, GATA3, PSA, synaptophysin, and chromogranin A. Thus, the tumor of epithelial cell origin was confirmed through AE1/AE3 positive staining." (PMID 41515615, 2026). "Immunohistochemistry showed that tumor cells were S100+, CD34+, SOX10+, c-kit−, desmin−, DOG1−, ER−, HMB45−, STAT6−, Oct4−, synaptophysin−, AE1/AE3−, SMA−, and vimentin+; for a small fraction of cells, EMA+, synaptophysin−, BCL2−, and β-catenin− and MIB-1 positivity was about 1%." (PMID 40777560, 2025). "Low or no expression of synaptophysin on routine ACC tumor specimens, albeit likely low in prevalence, could indicate a less NE-driven state (i.e., DLK1low/NOTCH1high/ABCB1low) with sensitivity to chemotherapy or an ADC." (PMID 40595495, 2025). "Negative immunolabelling against synaptophysin, S100, Iba-1, may exclude potential neuroendocrine, peripheral nerve sheath, and histiocytic origin of the tumor, respectively." (PMID 41180242, 2025). "Subcutaneous transplant tumour tissues (H128-Mut, control), BPM tumour tissues, and LM tumour tissues were subjected to IHC analysis, which showed that H128-LM and H128-BPM still have the expression of neuroendocrine markers, including CD56, CHGA, SYP and INSM1 (P > 0.05)." (PMID 38644473, 2024).
tumor (continued). "Concurrently, the strong positivity for smooth muscle actin, alongside the negativity for CD117, chromogranin A, and synaptophysin, suggests that the tumor is derived from smooth muscle cells rather than from interstitial cells of Cajal or neuroendocrine cells." (PMID 39896188, 2024). "Olig2 and synaptophysin IHC were positive in the tumor cells while GFAP was mostly negative." (PMID 39409964, 2024). "After completion of radiotherapy an increase of positive CTC markers – especially the epithelial (CK19, EpCAM) and neuroendocrine (SYP, CHGA) transcripts was observed, which led us to the hypothesis of increased CTC shedding due to the disruption of the tumor by radiation therapy." (PMID 39305397, 2024). "Immunohistochemical staining showed tumor cells positive for chromogranin A (CgA) and synaptophysin; no malignant features, such as lymphovascular invasion, significant atypia, or mitotic activity, were noted, leading to a diagnosis of a typical bronchial carcinoid tumor." (PMID 39233931, 2024). "CU-PC01 tumours display DNPC-like clinicopathological features, including the absence of AR, PSA and PSMA, loss of PTEN and RB, and a lack of NE markers, including SYP, neuronal differentiation 1 (NEUROD1), POU class 2 homeobox 3 (POU2F3) and achaete-scute homolog 1 (ASCL1)." (PMID 38667288, 2024). "Low or no expression of synaptophysin on routine ACC tumor specimens, albeit likely low in prevalence, could indicate a non-NE, less adrenocortical differentiated state (i.e. DLK1low/NOTCH1high/ABCB1low) with sensitivity to chemotherapy or an ADC." (PMID 39416174, 2024). "The mitotic rate of NECs is >20/mm2, and they usually stain positive for synaptophysin but may be negative for chromogranin A. EUS may be done to look for the depth of the tumor and local lymph node involvement." (PMID 39161532, 2024). "Interestingly, in contrast to the prominent NE tumor phenotype in DKO prostates, TKO prostates displayed an evident expression of luminal cell markers CK8 and AR and a downregulation of the NE marker SYP, supporting a function of ADORA2A in modulating PCa cellular plasticity." (PMID 38099497, 2023). "Immunohistochemically, the tumor cells were strongly and diffusely positive for CK and CK7, moderately positive for Dog-1, and negative for vimentin, P63, P40, napsin A, thyroid transcription factor 1, chromogranin A, CD56, synaptophysin, S-100, SRY-related HMG-box 10, and PAX8." (PMID 36820581, 2023). "Due to its extremely small tumor size, immunohistochemical staining for chromogranin A or synaptophysin could not be conducted." (PMID 37878146, 2023). "However, the tumor was postoperatively diagnosed as SSCT, which pathologically consisted of a tubular pattern with regular nuclei and embedded in a densely collagenous stroma, as well as diffusely positive for vimentin, β-catenin and synaptophysin." (PMID 37189109, 2023). "Some tumor sections were immunostained with ready-to-use primary antibodies against broad-spectrum cytokeratin (CK), vimentin, CD117, CK5/6, CK7, P40, P63, thyroid transcription factor-1 (TTF-1), smooth muscle actin, CD56, napsin A, synaptophysin, S-100, and Ki-67 (Maixin, Fuzhou, China)." (PMID 35550474, 2022). "There was no synaptophysin expression in the background hematopoietic cells with the tumor cells." (PMID 36401284, 2022). "The Ki67 proliferative index was 30%, and the tumor was negative for synaptophysin." (PMID 34986808, 2022). "Tumor cells did not express Desmin, Synaptophysin (SYP), Chromogranin and S100." (PMID 34508517, 2021). "NMYC is not amplified and the tumor is synaptophysin-, chromogranin A- and neurofilament-positive." (PMID 33671521, 2021). "The postoperative pathology showed the tumor cells to be positive for chromogranin, synaptophysin, cytokeratin, CD56 (partial weak), negative for vimentin, CD117, DOG-1, CD34, S-100, SMA, desmin, and Ki-67 approximately 2%, which confirmed the diagnosis of d-NETs." (PMID 33578581, 2021).
tumor (continued). "Similarly, the molecular characteristics of the SCLC tumor tissues were consistent with their matched SPDTOs under all culture conditions, as shown by immunohistochemical (IHC) analyses of CD56, chromogranin, and synaptophysin." (PMID 33572899, 2021). "Since many of these neoplasms do not co-express chromograninA, but only label with synaptophysin, we reviewed the literature to clarify the information about the rate of synaptophysin and chromograninA expression in the various entities of mesenchymal/non-epithelial neoplasms." (PMID 34350470, 2021). "The tumor cells are diffusively positive for vimentin and S-100, focally positive for glial fibrillary acidic protein, and generally negative for epithelial membrane antigen, synaptophysin, chromogranin A, and neurofilament." (PMID 31689841, 2019). "Moreover, at the diagnosis all tumours resulted positive for the NB markers NB84, SYP and CHGA." (PMID 31638925, 2019). "Three out of six tumours were strongly positive for synaptophysin, three were negative." (PMID 30297697, 2018). "However, the tumor cells were completely negative for other common neuroendocrine markers such as chromogranin A, synaptophysin, and TTF-1." (PMID 28103943, 2017). "Pathological analysis of the resected submucosal 1.8 cm tumour of the Meckel diverticulum confirmed a well differentiated neuro-endocrine tumour (grade I), whereas immunohistochemistry was positive for ACTH, chromogranin A and synaptophysin; Ki-67 score was < 1 %." (PMID 26610855, 2015). "Furthermore, D283ev tumor samples did not present immunoreactivity for synaptophysin, a marker of differentiated cells." (PMID 26491983, 2015). "The tumor cells expressed p63 and ck5/6 but not chromogranin and synaptophysin." (PMID 25494951, 2014). "Diagnosis of metastatic renal cell carcinoma (RCC) was confirmed by immunohistochemical stains, which showed the tumor cells to be positive for CD10, vimentin and pancytokeratin, but negative for CK7, carcinoembryonic antigen (CEA), chromogranin, synaptophysin and CD68." (PMID 23305230, 2013). "Also we used Chromogranin A and Synaptophysin to exclude the neuroendocrine differentiation of the tumor, where we observed that, these markers were negative." (PMID 22867429, 2012). "Our case highlights two unusual manifestations of precursor T-ALL/T-LBL, namely, the rare initial presentation of cholestatic jaundice and the aberrant expression of synaptophysin by the tumor cells both of which, to the best of our knowledge, have not been reported before." (PMID 19284608, 2009). "The tumor cells were positive for chromogranin, synaptophysin, cytokeratin and negative for S-100." (PMID 17931412, 2007). "However, if a NET is negative for synaptophysin, then a different marker for neuroendocrine differentiation (e.g. chromogranin-A) could be used to identify tumor cells." (PMID 32632119, 2020). "INI-1 was retained in the tumor cells, and WT1, desmin, myogenin, BCOR, TLE-1, CD45CLA, and synaptophysin were all negative (not shown)." (PMID 41230381, 2026). "Cytopathological analysis of the lymph nodes showed tumor cells positive for p16, CAM5.2, TTF-1, synaptophysin, and CD56, and negative for CD45, p40, chromogranin, Napsin A, p63, and CK5/6." (PMID 41589095, 2026). "The tumor cells were immunohistochemically positive for GFAP, ATRX, and H3 K27me3, but negative for synaptophysin, IDH1 R132H, and H3 K27M." (PMID 39432011, 2025). "The tumor cells expressed NSE and cytokeratin AE1/AE3, but were immunohistochemically negative for synaptophysin, chromogranin A, calcitonin, S-100 protein, GFAP, NFH, and MAP-2, which in our opinion supports the diagnosis of NEC." (PMID 39974159, 2025). "Immunohistochemically, the tumor cells were positive for GFAP and S‐100 protein, weakly positive for SOX2, focally positive for synaptophysin, and negative for TTF‐1, neurofilament protein, NeuN, EMA, chromogranin, and BCOR." (PMID 39492623, 2025).
tumor (continued). "The immunophenotype of the tumor did not reveal a clear line of origin, with negative staining for GFAP, OLIG2, S100 protein, SOX10, desmin, pankeratin, synaptophysin, and only focally positive vimentin." (PMID 40159593, 2025). "Immunohistochemical studies confirmed the diagnosis, with tumor cells positive for pancytokeratin, TTF1, synaptophysin, and INSM1, and negative for Napsin-A, p40, WT1, calretinin, and chromogranin." (PMID 40403473, 2025). "Tumor cells tested negative for SMARCA4 but were positive for Chromogranin-A(CgA), Synaptophysin (SYN), Insm-1, TTF-1 (partial), and Ki67 (90%)." (PMID 40661782, 2025). "In our case, immunohistochemical analysis of the tumor’s tissue showed immunopositivity for FLI1-1, while it was negative for synaptophysin." (PMID 38459600, 2024). "The tumor cells expressed CD99, synaptophysin, CD56, MUC4, and EMA (focal), but not AE1/AE3, S100, smooth muscle actin, desmin, CD34, chromogranin A, GFAP, NKX2-2, PAX7, and INSM1." (PMID 39249507, 2024). "Through staining of CD4, CD8, HLA-DR, Ki-67, MHC-I, and synaptophysin, the level of MHC-I+ and MHC-II+ tumor cells in ONB were interrogated as a potential mechanism responsible for the lack of T cell tumor parenchyma trafficking." (PMID 38822345, 2024). "The tumor cells were negative for GFAP, Olig-2, and only individual tumor cells expressed synaptophysin." (PMID 38926750, 2024). "The tumor cells showed patchy staining for INSM1 and synaptophysin, but were negative for AE1/AE3, CAM5.2, p40, chromogranin, S100, HMB45, NKX2.2, desmin, CD45 (LCA), CD3, and CD20, with intact INI1 and BRG1 expression." (PMID 39404971, 2024). "Among other immunostains not shown, ATRX nuclear expression was retained in all tumor cells, and none of the tumor cells were positive for IDH1 R132H mutant protein, napsin, NKX3.1, CD45, synaptophysin, INSM1, SOX10 protein, p40, CDX2 protein, PSAP, or PSA." (PMID 38845695, 2024). "The original tumor was histologically pure SCCC, positive for neuroendocrine markers such as synaptophysin, chromogranin A, and CD56, and negative for Alcian blue staining." (PMID 36691316, 2023). "The neoplasm was positive for CK7, CK19, and synaptophysin; weakly positive for pCEA and chromogranin; and negative for nuclear β-catenin, Hep-Par1, glypican-3, alpha-fetoprotein, and glutamine synthetase." (PMID 36782322, 2023). "Histomolecular examination shows oligodendrocyte-like tumour cells positive for OLIG2, Synaptophysin, MAP2 and S100 but negative for IDH1 R132H." (PMID 36831464, 2023). "Immunostaining of TK-EPN862 tumor cells was consistent with the features of EPN, including negative staining for OLIG2 and synaptophysin, positive staining for GFAP, and intracytoplasmic dot-like positivity for EMA." (PMID 36937401, 2023). "In vivo, although reduction of CELSR3 did not impact NEPC tumor growth rate or metastatic potential, we did find that reduction of CELSR3 resulted in a diminution of NEPC markers (e.g., SYP, ASCL1, INSM1, SYP, and CHGA) in vitro and in vivo." (PMID 37546702, 2023). "Tumor cells were predominantly negative for OLIG2 and synaptophysin, positive for GFAP and demonstrated intracytoplasmic dot-like EMA staining." (PMID 36937401, 2023). "The EWS tumor cells usually express CD99, vimentin, synaptophysin (Syn), and neuron-specific enolase (NSE) but do not express common antigen (LCA), CD20, and chromaffin granin (CgA)." (PMID 37469664, 2023).
tumor (continued). "These areas merged in a continuous fashion with another part of the tumor showing no p40/CK5 positivity as well as diffuse and strong CD56, Chromogranin and synaptophysin reactivity." (PMID 35538551, 2022). "Markers vimentin, synaptophysin, MENA, ECAD and CK20 had lower expression in the tumour tissue relative to that in the non-tumour tissue with the exception of MENA for one patient and CK20 for another patient." (PMID 36362433, 2022). "The best markers proved to be synaptophysin (highly specific, but occasionally also weakly staining connective tissue cells), and tyrosine hydroxylase (although often negative in primary HNPGL tumours and derived cultures)." (PMID 36178902, 2022). "Parts of the tumor demonstrated p40 and CK5 positivity, together with negative to patchy neuroendocrine positivity (60% CD56, 30% chromogranin and 50% reactivity with synaptophysin)." (PMID 35538551, 2022). "Tumor cells were negative for vimentin, CK7, smooth muscle actin, napsin A, synaptophysin, S-100, and TTF-1." (PMID 35550474, 2022). "Core biopsy of left chest wall nodule also revealed poorly differentiated LUAD with tumor cells positive for pan-keratin and TTF-1 and negative for ER, PR, CDX2, WT1, PAX-8, synaptophysin and chromogranin." (PMID 35546239, 2022). "Immunohistochemical staining of the tumour was positive for Renin, CD34, Vimentin, and synaptophysin (Syn) and negative for somatostatin receptor 2 (SSTR2) and chromogranin A (CgA)." (PMID 35303838, 2022). "Even though 30% of organoids expressed CD56, the original tumor showed only limited CD56 expression, which did not track closely with expression of synaptophysin." (PMID 33776923, 2021). "As immunohistochemical analyses showed the tumor cells to be negative for CD56, chromogranin A, synaptophysin, and PSA, the definitive diagnosis was ASCP." (PMID 34479548, 2021). "Tumor cells were negative for GFAP, synaptophysin, keratins (Cam5.2, pancytokeratin), inhibin, carbonic anhydrase, PAX8, and D2-40." (PMID 34925233, 2021). "The original tumor from NEC-01010 was negative for chromogranin and showed heterogeneous synaptophysin expression (50% overall, varying from absent to strong, both in solid and in glandular parts of the tumor." (PMID 33776923, 2021). "Immunohistochemically, tumor cells were negative for Arg-1, glypican-3 (GPC3), hepatocyte specific antigen (HSA), and positive for synaptophysin (Syn), α-inhibin, and Melan A. The Ki-67 index was 1 %." (PMID 34218806, 2021). "Pathologic analysis of the biopsy revealed a high grade, poorly differentiated neoplasm and immunohistochemical studies revealed tumor cells positive for AE1/AE3 and synaptophysin while negative for CD3, CD20, PAX5, chromogranin, TTF-1, CDX2 and CDH17." (PMID 34479480, 2021). "GCA usually shows immunoreactivity for neuroendocrine markers, such as chromogranin A, synaptophysin, and CD56 in variable numbers of tumor cells, but these stains are not required for diagnosis." (PMID 34804955, 2021). "Immunohistochemical analyses revealed that the tumor cells were negative for CD56, chromogranin A, synaptophysin, and PSA." (PMID 34479548, 2021). "The tumor cells were positive for cytokeratin (CK), CD56, chromogranin (CGA), neuron-specific enolase (NSE), and synaptophysin (Syn), and were negative for vimentin and S100." (PMID 32245475, 2020). "The tumor cells were negative for CD117, DOG1, SMA, desmin, S-100, synaptophysin, and chromogranin A. On the basis of the histology and immunostaining profile, the tumor was diagnosed as a malignant SFT of the pancreas." (PMID 33188464, 2020). "These tumor cells were negative for the basal epithelial cell markers p63 and CK5 (Fig 3D6-7), as well as for the neuroendocrine cell marker synaptophysin (Fig 3D8)." (PMID 30677079, 2019).